LATS1 (large tumor suppressor kinase 1)
Diseases named in the same sentence as LATS1 in open-access papers (continued):
Sharing a sentence is not in itself a finding about the gene and the disease.
gastric cancer (40 papers, 2015 to 2025). A primary or metastatic malignant neoplasm involving the stomach. "In breast cancer, colorectal cancer, gastric cancer, and lung cancer, decreased LATS1/2 expression is associated with lymph node metastasis." (PMID 39936032, 2025). "The decreased expression of LATS1 is inversely correlated with lymph node metastasis in gastric cancer, and one of the reasons for loss of LATS1 expression lies in the hypermethylation of LATS1 in the promoter regions." (PMID 25712415, 2015). "More interestingly, the in vivo ubiquitination assays revealed that the endogenous ubiquitination of LATS1 protein was markedly suppressed upon WWP2 downregulation in gastric cancer cells." (PMID 36803368, 2023). "Leukaemia inhibitory factor (LIF) activated tumor-suppressive LATS1/2 to diminish gastric cancer stemness cells (CSCs) and enhance the cancer-killing effect of 5-FU and doxorubicin." (PMID 36289774, 2022). "It has been shown that there is a close relationship between abnormally expressed LATS1 and the abnormal proliferation and apoptosis of various cancer cells such as gastric cancer, skin cancer and metastatic prostate cancer." (PMID 35435136, 2022). "Ubiquitination and the subsequent degradation of LATS1/2 abrogate the Hippo pathway and worsen gastric cancer (GC)." (PMID 35210431, 2022). "For examples, circular RNA_LARP4 (circLARP4) is downregulated in gastric cancer and sponges to miR-424 by circRNA expression profile and bioinformatic analysis and inhibits biological behaviors of gastric cancer by affecting LATS1 expression." (PMID 34489401, 2021). "CircLARP4, a cytoplasmic cirRNA, was found to inhibit the proliferation and invasion of gastric cancer cells by sponging miR-424-5p and regulating LATS1 expression." (PMID 31189743, 2019). "In gastric cancers, overexpression of Cul4A promoted gastric cancer cell proliferation and epithelial–mesenchymal transition by downregulating LATS1-Hippo-YAP signaling." (PMID 31052599, 2019). "In agreement with the gene expression profiling study, we found that UA increased the expression of the Hippo signaling pathway proteins Mst1, Mst2, p-Mob1, and LATS1 in gastric cancer cells." (PMID 31547587, 2019). "While antral stem cells expressing Lgr5, Mist1 or Sox2 may be among the gastric cancer origin cells in the setting of Apc loss, Lgr5+ cells have been implicated in more invasive types of gastric cancer, characterized by the simultaneous loss of Pten and Smad4, or by the loss of Lats1 and Lats2." (PMID 30384487, 2018). "As a tumor suppressor, circLARP4 is downregulated in gastric cancer (GC) tissues, suppressing gastric tumorigenesis and progression by sponging miR-424 and increasing LATS1 expression." (PMID 30111313, 2018). "For example, circular RNA_LARP4 expression positively correlates with the tumor suppressor LATS1, the direct target of miR-424-5p in gastric cancer." (PMID 30458784, 2018). "LATS1 expression is frequently reduced in gastric cancer tissues, and the absence of LATS1 expression is correlated with tumor invasion, poor prognosis, and recurrence in gastric cancer patients." (PMID 39936032, 2025). "Large tumor suppressor kinase 1 (LATS1), one of the predominant components of the Hippo pathway, has been characterized as a key player controlling the proliferation and invasion of cancer cells, including gastric cancer (GC) cells." (PMID 36803368, 2023). "Sequencing analysis showed that miR-424-5p was negatively and strongly correlated with the expression of LATS1, and therefore miR-424-5p could promote the proliferation of gastric cancer cells through LATS1." (PMID 35409396, 2022). "Circular RNA_LARP4, which could be used as a sponge to adsorb miR-424-5p and regulate LATS1 expression to inhibit the proliferation and invasion of gastric cancer cells, was also localized in the cytoplasm." (PMID 35087744, 2021).
gastric cancer (continued). "Given the facts that LATS1 is a critical regulator of YAP1 5 and YAP1 can upregulate Gli1 expression in esophageal squamous cell carcinoma 30 and gastric cancer 31, we speculated that YAP1 might be implicated in LATS1-mediated Gli1 suppression." (PMID 35003351, 2021). "Moreover, circLARP4 inhibited the development and metastasis of gastric cancer cells by targeting the miR-424/LATS1 axis." (PMID 34348712, 2021). "Furthermore, a reduced MST1/2 and LATS1 expression was found in gastric cancer, and tumors with lymph node metastasis showed minimal levels of LATS1." (PMID 34206989, 2021). "For example, deletion of CCDC80 impairs the growth-inhibitory effect mediated by LATS1/2 (Hippo pathway kinases) deficiency in MC38 cells, and silencing the immune-infiltration-associated gene CCDC80 suppresses malignant progression and tumorigenicity in gastric cancer." (PMID 40534859, 2025). "Our previous studies indicated that large tumor suppressor kinase 1 (LATS1), a core part of Hippo signaling pathway, functions as a tumor suppressor in gastric cancer (GC)." (PMID 28893265, 2017). "Treatment of gastric cancer cells and human xenografts in mice with ursolic acid activated the kinases MST1, MST2, and LATS1 and inhibited YAP1, leading to decreased proliferation and metastases." (PMID 39768557, 2024). "In gastric cancer cells, CLDN6 was reported to interact with LATS1/2 and reduce the level of p–YAP, thereby increasing the nuclear YAP activity." (PMID 35008557, 2021). "In gastric cancer cells, CLDN6 interacted with LATS1/2 and decreased the conversion of LATS into p-LATS, thereby inhibiting the Hippo signaling pathway." (PMID 34948213, 2021). "In lung and gastric cancers, WBP2 has been shown to be a promoter of LATS1/2 kinase activities through interactions with critical regulatory components to inactivate Hippo signalling." (PMID 34831354, 2021). "On the other hand, downregulation of LATS1/2 correlated with a poorer prognosis (such as tumour, node and metastasis (TNM) stage and distal metastasis) in gastric cancer." (PMID 34831354, 2021). "In the context of lung and gastric cancers, WBP2 has been shown to negatively regulate LATS1 and LATS2 kinase activity through WW domain-dependent and WW domain-independent mechanisms, respectively." (PMID 34831354, 2021). "The role of LATS1/2 in the prognosis of different subtypes of advanced gastric cancer and its relationship with the tumor immune microenvironment in GC remain unknown." (PMID 32983971, 2020). "Similar to the gene expression profiling results, the protein levels of RASSF1, MST1, MST2, LATS1, and p-YAP were increased, whereas those of CTGF were decreased by UA in gastric cancer cells." (PMID 31547587, 2019). "However, the contribution of LATS1 to gastric carcinoma (GC) remains unclear." (PMID 26921249, 2016). "Additionally, CLDN6 interacts with LATS1/2 to reduce LATS1/2 and YAP1 phosphorylation, influence YAP1 entry into the nucleus, and enhance the invasive ability of gastric cancer cells." (PMID 36620607, 2022). "Moreover, our previous study revealed that pseudogene DUXAP10 is over-expressed in gastric cancer, and promoted cell proliferation and invasion via interacting with EZH2 and LSD1 to repress LATS1 transcription." (PMID 34660601, 2021). "In gastric cancers, expression of the Hippo pathway transcription factors YAP1 and TEAD was up-regulated in parallel with CDX2, while the negative regulators of the pathway, serine/threonine kinases MST1 and LATS1, were down-regulated, compared with normal gastric epithelia." (PMID 39768557, 2024). "We then assessed the interaction of AGK and Hippo‐YAP1 pathway in gastric cancer cells and found that AGK overexpression was able to up‐regulate level of YAP1 and CTGF proteins, but lead to a down‐regulation of the level of LATS1/2 and p‐YAP without changing in MST1/2 levels." (PMID 32827244, 2020).
gastric cancer (continued). "Many studies have found that large tumor suppressor kinase 1 (LATS1) and LATS2 play important roles in many diseases, but studies have been rare on the relationship between these genes and non-cardia gastric cancer (GC)." (PMID 32423384, 2020).
hepatocellular carcinoma (36 papers, 2013 to 2025). A malignant tumor that arises from hepatocytes. "LATS1, Mob1, and YAP were shown to be deficient in hepatocellular carcinoma, and the phosphorylation of LATS1, Mob1, and YAP could activate the Hippo pathway and thereby suppressed tumors." (PMID 37548821, 2023). "lncRNA uc.134 inhibits the aggressiveness of hepatocellular carcinoma via suppressing CUL4A-mediated ubiquitination of LATS1." (PMID 37013491, 2023). "Overexpressed lncRNA pik3cd-as1 has been shown to promote LATS1 expression by competitively binding to miR-566, which resulted in the inhibition of hepatocellular carcinoma cell growth, invasion, and metastasis." (PMID 36248853, 2022). "A study discovered that a new lncRNA called uc.134 slows the growth of hepatocellular cancer by preventing LATS1 from being ubiquitinated by CUL4A." (PMID 36267408, 2022). "For example, LncRNAuc.134 inhibits the progression of hepatocellular carcinoma by inhibiting CUL4A-mediated LATS1 ubiquitination." (PMID 35860629, 2022). "For instance, lncRNA uc.134 inhibits CUL4A-mediated ubiquitination of LATS1 to hinder hepatocellular carcinoma progression." (PMID 33568633, 2021). "Uc.134, a novel lncRNA, elevates YAPS127 phosphorylation and represses LATS1 ubiquitination mediated by CUL4A to inhibit the progression of hepatocellular carcinoma." (PMID 34401209, 2021). "For example, one study indicated that uc.134 represses hepatocellular carcinoma development by inhibiting CUL4A-mediated ubiquitination of LATS1 and that uc.416 inhibits miR-153 and promotes epithelial-to-mesenchymal transition in renal cell carcinoma." (PMID 32303004, 2020). "Our study identifies that a novel lncRNA, uc.134, represses hepatocellular carcinoma progression by inhibiting the CUL4A-mediated ubiquitination of LATS1 and increasing YAPS127 phosphorylation." (PMID 28420424, 2017). "For instance, CUL4A mediates the ubiquitination of LATS1 to regulate YAP activity in hepatocellular carcinoma, AGK inhibits the activation of the Hippo pathway proteins in GC38 and CD44 functions upstream of the Hippo signalling pathway and attenuates its activation in glioblastoma." (PMID 37555915, 2023). "Research has shown that LMO3 directly interacts with large tumor suppressor kinase (LATS) 1 to inhibit the phosphorylation of LATS1 and promote Rho GTPases activities, thus suppressing Hippo signal to promote the invasion and metastasis of hepatocellular carcinoma." (PMID 35350839, 2022). "Certainly, a notable proportion of lncRNAs have also been found to regulate protein expression through ubiquitination: lncRNA uc.134 could repress hepatocellular carcinoma progression by inhibiting the CUL4A-mediated ubiquitination of LATS1 and increasing YAPS127 phosphorylation." (PMID 32351584, 2020). "LATS1 KO mice develop fibrosarcomas by 4-10 months of age whereas disruption of other key components of the HIPPO pathway has led to the development of many tumor forms in mice including hepatocellular carcinoma, Schwannoma, squamous cell carcinoma or malignant mesothelioma." (PMID 27409837, 2016). "PRMT1 facilitates the asymmetric di‐methylation of YAP at arginine 124, thereby diminishing the interaction between YAP and LATS1, inhibiting subsequent phosphorylation of YAP, and promoting both YAP activity and cell proliferation in hepatocellular carcinoma." (PMID 39367565, 2024). "LATS1, the key regulator of the Hippo pathway, was found to be a binding partner of LMO3 during tumorigenesis of hepatocellular carcinoma." (PMID 35350839, 2022). "In hepatocellular carcinoma, LMO3 directly interacts with LATS1 and suppressing Hippo signaling to promote invasion and metastasis." (PMID 32195177, 2020). "Knockdown of LATS1 or YAP by siRNA blocked the effects of TNFAIP8 on cell proliferation, suggesting that TNFAIP8 promotes hepatocellular carcinoma progression through LATS1-YAP signaling pathway." (PMID 30586922, 2018).
hepatocellular carcinoma (continued). "First, liver specific deletion of MST1/2 in mice causes hepatocellular carcinoma (HCC) by YAP deregulation without any apparent involvement of LATS1/2." (PMID 23985307, 2013). "With markedly lower expression in hepatocellular carcinoma, miR-29c-3p can inhibit tumors by targeting DNA methyltransferase 3B (DNMT3B) and the Hippo signaling pathway involving large tumor suppressor kinase 1 (LATS1)." (PMID 34956559, 2021). "Several reports have shown that PDK1 can form complex with the Hippo components including MST1/2, SAV1, LATS1/2, and PDK1 recruited to the plasma membrane triggered by PI3K leads to dissociation of these complex and YAP activation in MCF-10A, HEK293T, and hepatocellular carcinoma cells." (PMID 34725466, 2021). "Although LATS1 and LATS2 kinases, core components of the mammalian Hippo pathway, have been shown to exert tumor suppressive activities, here we report a pro-survival role of LATS1 but not LATS2 in hepatocellular carcinoma (HCC) cells." (PMID 31848340, 2019). "In hepatocellular carcinoma, TNFAIP8 interacts with large tumor suppressor kinase 1 (LATS1), a serine/threonine-protein kinase, and overexpression of TNFAIP8 inhibits Yes-associated protein (YAP) phosphorylation, resulting in nuclear localization and stabilization of YAP." (PMID 30586922, 2018). "In hepatocellular carcinoma (HCC) tissues, Chen reported that α-actinin-1 competitively interacts with MOB1 and decreases the phosphorylation of LATS1/YAP to regulate Hippo signaling activity." (PMID 41153762, 2025). "Further, in QGY7703 and SMMC7721 hepatocellular carcinoma (HCC) cells, NEDD4 increased cell migration and invasion via inhibiting the tumor suppressor LATS1." (PMID 36293239, 2022).
glioma (22 papers, 2012 to 2024). A benign or malignant brain and spinal cord tumor that arises from glial cells (astrocytes, oligodendrocytes, ependymal cells). "For example, low expression of LATS1 was reported in glioma and decreased LATS1 expression was associated with unfavorable prognosis." (PMID 39166861, 2024). "LATS1 is susceptible to being a molecular target that is mediated by various factors,and is consequently engaged in the development of glioma 32-34." (PMID 37151881, 2023). "Deficiency of LATS1 directly brings about the tumor formation of soft-tissue sarcomas and ovarian tumors in mice and facilitates the progression of glioma." (PMID 26921249, 2016). "To investigate the prognostic value of LATS1 expression for glioma, we assessed the association between levels of LATS1 expression and patients’ survival using Kaplan–Meier analysis with the log-rank test." (PMID 22909338, 2012). "Interestingly, reduced LATS1 expression was negatively correlated with tumor grade in glioma patients and was associated with significantly shorter overall survival time." (PMID 33477668, 2021). "Furthermore, oncogenic YAP1 activation occurs as a consequence of a loss in NF2-dependent inactivation of LATS1 (a key inhibitor of YAP1), and decreased LATS1 activity has also been associated with glioma progression." (PMID 29440180, 2018). "We also observed that overexpressed LATS1 caused the G2/M phase blockade in glioma U251 cells." (PMID 22909338, 2012). "In addition, we found that LATS1 expression levels were inversely associated with WHO grade of glioma and KPS." (PMID 22909338, 2012). "The results indicated that S100A16 predicted poor prognosis in glioma by promoting cell proliferation, migration and invasive abilities via inhibiting LATS1 expression in the Hippo pathway." (PMID 37151881, 2023). "Compared with normal brain tissues, the expression levels of LATS1 and LATS2 are significantly decreased in glioma tissues and are associated with poor prognosis." (PMID 37423952, 2023). "LATS1 overexpression not only significantly inhibits migration, invasion cell growth and also delays cell cycle progression from G2/M to G1 in vitro glioma U251 cells." (PMID 33773564, 2021). "Although LATS1/2 are considered as tumor suppressors, RASSF1/LATS2-coupled promoter hypermethylation was found to be associated with better overall survival in glioma patients." (PMID 33477668, 2021). "LATS1 is downregulated in several human cancers such as astrocytoma, colorectal cancer, lung cancer, breast cancer, and glioma due to hypermethylation." (PMID 33773564, 2021). "In a previous study, we demonstrated that LATS1 was downregulated in astrocytoma due to promoter hypermethylation, and that restoration of expression induced apoptosis in glioma cells." (PMID 31605013, 2020). "LATS1 has been identified as a tumor suppressor, and decreased expression of LATS1 has been correlated with poor prognosis in glioma patients." (PMID 31605013, 2020). "Our pervious study also identified that YAP1/TAZ increased and meanwhile those of p-YAP1/p-TAZ and LATS1/2 decreased in gliomas." (PMID 28962630, 2017). "Previous studies have shown that the expression of LATS1 is downregulated in malignant mesothelioma, glioma, NSCLC and ovarian tumors and represents an independent prognostic indicator for the survival and prognosis of patients with glioma and ovarian cancer." (PMID 26921249, 2016). "The tumor suppressor LATS1 is down regulated in various soft tissue sarcomas, and LATS1 down-regulation was shown to be a poor prognostic factor in glioma cases." (PMID 25628642, 2014). "According to multivariate analyses, decreased expression of LATS1 protein was a significant predictor of poor prognosis for glioma patients." (PMID 22909338, 2012). "Similar to reports of other tumor types, we observed that LATS1 expression was significantly decreased in 13 glioma tissues compared to their matched normal tissues." (PMID 22909338, 2012).